RN7SL107P (RNA, 7SL, cytoplasmic 107, pseudogene)
Gene: Miscellaneous RNA gene on chromosome 8 (80,613,544 to 80,613,826, reverse strand). Ensembl gene ENSG00000243424.
Homologues: Orthologues: chimpanzee Metazoa_SRP (99% identical), macaque Metazoa_SRP (92% identical), rabbit Metazoa_SRP (69% identical). Paralogues in human: RN7SL1 (86% identical), RN7SL2 (85% identical), RN7SL3 (84% identical), RN7SL357P (84% identical), RN7SL481P (83% identical), RN7SL182P (82% identical), RN7SL45P (82% identical), RN7SL786P (82% identical), RN7SL408P (82% identical), RN7SL88P (82% identical), RN7SL448P (81% identical), RN7SL230P (81% identical), and 703 more.